PAX8 (paired box 8)
Diseases named in the same sentence as PAX8 in open-access papers (continued):
Sharing a sentence is not in itself a finding about the gene and the disease.
endometriosis (14 papers, 2013 to 2026). The growth of functional endometrial tissue in anatomic sites outside the uterine body. "Immunostaining with estrogen receptor (ER) and paired box gene (PAX8) were positive, further supporting the diagnosis of endometriosis." (PMID 38528142, 2024). "It was proposed that these tumor types arise from endometriosis, PAX8-positive endometrial cells ectopically expressed outside the uterus." (PMID 35806410, 2022). "PAX8 specificity has been demonstrated in several cases of normal and neoplastic tissue and very recently in extragenital endometriosis." (PMID 34681634, 2021). "Recently, our group reported the usefulness of PAX8 as an endometriotic epithelial marker in the diagnosis of extragenital endometriosis, including thoracic endometriosis." (PMID 33071634, 2020). "The 5 PAX8+/Calretinin-cases in this category represented endosalpingiosis (n = 4) and endometriosis (n = 1)." (PMID 23958394, 2013). "PAX8 is a highly sensitive epithelial marker for extragenital endometriosis." (PMID 38528142, 2024). "However, in endometriosis expression of other markers of Müllerian origin such as ER, PR and PAX8 will help to distinguish it from SS." (PMID 36910640, 2023). "Only a few cases of ovarian SMBT with endometriosis showed expression of PAX2 and conversely, most of the cases showed expression of PAX8." (PMID 35387670, 2022). "Napsin-A, racemase, and PAX-8 were positive, consistent with CCC, likely arising within a c-section endometriosis focus." (PMID 31396428, 2019). "In all 8 cysts derived from three iPD mice, Pax8-positive cells lacked the expression of Pten and showed stratification and nuclear atypia corresponding to atypical endometriosis." (PMID 37221199, 2023). "FRA expression was negative in all Pax-8 negative OSE as well as in all Pax-8 negative OEIs (surface epithelium derived ovarian inclusions) from the 30 ovarian sections without endometriosis examined (data not shown)." (PMID 36936232, 2023). "In immunohistochemical patterns, there was a statistically significant difference in PAX2 and PAX8 expression between in ovarian SMBT with or without endometriosis (P = 0.016, P < 0.001)." (PMID 35387670, 2022). "In contrast, all patients with endometriosis showed positive PAX8 expression, whereas only 14 of 22 (63.6%) patients without endometriosis showed positivity (P < 0.001)." (PMID 35387670, 2022). "There was a difference in PAX2 and PAX8 expression between in ovarian SMBT with or without endometriosis." (PMID 35387670, 2022). "The exact mechanism explaining how endometriosis is related to the development or progression of ovarian SMBT is not clarified yet, however, it has become clear that Müllerian markers such as PAX2 and PAX8 show distinctively different expression pattern between SMBTs with and without endometriosis." (PMID 35387670, 2022). "In conclusion, only a few cases of ovarian SMBT with endometriosis showed expression of PAX2 and conversely, most of the cases of ovarian SMBTs with endometriosis showed expression of PAX8 in contrast to SMBTs without endometriosis." (PMID 35387670, 2022). "SMBT with endometriosis in this study showed similar expression patterns of PAX2 and PAX8 with those in endometrioid tumors, in contrast to SMBT without endometriosis." (PMID 35387670, 2022). "In our study, a few cases of SMBT with combined endometriosis showed positive expression of PAX2 and most cases showed positive expression of PAX8 in contrast to SMBTs without endometriosis." (PMID 35387670, 2022).
mucinous ovarian cancer (14 papers, 2014 to 2025). An invasive malignant neoplasm that arises from the ovary and is characterized by the presence of malignant epithelial cells that contain intracytoplasmic mucin and may resemble the epithelial cells of the endocervix or gastrointestinal tract. "Despite limited previous studies that only assessed PAX8 expression in mucinous carcinomas, a recent study confirmed PAX8 expression in MBT as well as ovarian mucinous carcinoma." (PMID 35909430, 2022). "PAX8 shows a high level of expression in non-mucinous ovarian carcinomas; in contrast, mucinous carcinomas of the ovary show lower levels of expression and, when positive, are typically focal." (PMID 33504059, 2021). "In primary mucinous ovarian cancer, the immunohistochemistry expression of PAX8 is usually low." (PMID 39358778, 2024). "While immunohistochemistry is often inconclusive, PAX-8 might prove useful as a marker relatively specific for mucinous ovarian carcinomas." (PMID 25894432, 2015). "In general, the typical primary mucinous ovarian carcinomas are CK7-positive, with diffuse co-expression of CK20 and CDX2, PAX8 and SATB2-negative, while AMNs are CDX2, CK20, and SATB2-positive, and PAX8 and CK7-negative." (PMID 40475008, 2025). "While limited previous studies had only assessed PAX8 expression in mucinous carcinomas (10/25; 40% expression), a recent study confirmed expression of PAX8 in MBT (14/23; 61%) as well as ovarian mucinous carcinomas (11/24; 46%)." (PMID 28025670, 2017). "The differential diagnosis of MOC requires a combination of other indicators such as CK7, CK20, CDX2, PAX8, SATB2, and claudin 18.2, which may further reduce the misdiagnosis and missed diagnosis of mucinous ovarian cancer." (PMID 37664708, 2023). "Of note, all non-mucinous EOC subtypes are PAX8-positive in the vast majority of tumors, and only mucinous ovarian carcinomas are mostly PAX8-negative, suggesting a different embryonic origin." (PMID 35806410, 2022). "PAX8, a marker of Müllerian origin expressed in tissues including the ovary, fallopian tube, and endometrium, is positive in most endometrioid, serous, and clear cell ovarian carcinomas, occasionally positive in mucinous ovarian carcinomas, and typically negative in Krukenberg tumors." (PMID 41517393, 2025).
metastatic tumors (13 papers, 2014 to 2026). "Moreover, somatic mutations of NBN, p.P6S, and PAX8, p.R49H were observed in the metastatic tumor." (PMID 29535844, 2018). "Our IHC analysis of archival lung tumor tissues unmistakably showed that the majority of large cell carcinoma (94%), adeno carcinoma (80%), squamous cell carcinoma (100%), and metastatic tumors in lymph nodes (93%) were positive for PAX8 expression (n = 254)." (PMID 24628993, 2014). "Immunohistochemical H&E and PAX-8 staining confirmed metastatic tumors." (PMID 35864492, 2022). "The metastatic tumor harbored somatic mutations in NBN, p.P6S, and PAX8, p.R49H." (PMID 29535844, 2018). "No major differences were noted with respect to PAX8 expression when primary tumors were compared with metastatic tumor samples." (PMID 24628993, 2014). "GATA3, TTF-1, S100, p40, PAX8, p63, NKX3.1, CDX2, SALL4, CD30 (-) were detected to rule out metastatic disease." (PMID 40978995, 2025).
cyst (12 papers, 2014 to 2026). A sac-like closed membranous structure that may be empty or contain fluid or amorphous material. "Secondly, Pax8 immunoreactivity can be observed in islet cells, and sometimes such Pax8 immunoreactive islet cells can be quite close to the cyst luminal surface, causing a diagnostic pitfall." (PMID 37098593, 2023). "For instance, postnatal overexpression of VEGF in renal tubules of Pax8-rtTA/(tetO)7VEGF mice causes capillary-rich interstitial fibrosis, cyst formation and disruption of glomerular architecture." (PMID 27454431, 2016). "Nuclear PAX2 expression, and cytoplasmic PAX8 expression were found to be up-regulated in cyst-lining epithelial cells." (PMID 41501598, 2026). "The cyst-lining epithelium expresses PAX8, PAX2, and CK7, while the subepithelial stromal region shows strong positive staining for ER, PR, CD10, Melan-A, and HMB45." (PMID 41426332, 2025). "Additional hematoxylin and eosin deeper sections will be helpful to determine if the Pax8 immunoreactive cells are truly cyst luminal cells or lymphoid aggregates." (PMID 37098593, 2023). "We evaluated immunophenotypic features of immortalized HOVs-cyst-1 cells and found diffuse expression of pan-cytokeratin and PAX8." (PMID 35326657, 2022). "The cyst lining is typically positive for estrogen receptor (ER), progesterone receptor (PR), PAX-8, and WT1 immunohistochemical stains." (PMID 28070193, 2016). "In this instance, the cyst was located in the upper thigh and showed strong staining not only for ER and PR but also for PAX-8 and WT1." (PMID 28070193, 2016). "In additional immunohistochemical analysis of cyst wall showing collecting duct markers, epithelial membrane antigen (EMA), the paired box (PAX) 2 and PAX8, were positive in the lining cell of the cyst wall." (PMID 25038818, 2014). "In immunohistochemical analysis of cyst wall showing the cystic change, collecting duct markers, EMA, PAX2 and PAX8, were positive in the lining cell of the cyst wall." (PMID 25038818, 2014). "In such situations, additional hematoxylin and eosin deeper sections may be helpful to determine if the Pax8 immunoreactive cells are truly cyst luminal cells or adjacent islet cells." (PMID 37098593, 2023). "By immunohistochemistry, estrogen receptor (ER), progesterone receptor (PR), PAX-8, and WT1 were positive in the epithelial lining of the cyst, lending support to a possible Müllerian origin." (PMID 28070193, 2016). "Histopathology revealed a cyst lined by cuboidal epithelium, positive for Claudin4, estrogen receptor, Wilms' Tumor 1 (WT1), and Paired box gene 8 (PAX8), and negative for Calretinin, findings consistent with a Müllerian duct cyst." (PMID 41728454, 2026). "The cyst epithelia stained intensely positive for human bone marrow endothelial marker-1 (HBME-1) and cytokeratin 5/6, and negative for paired box protein 8 (PAX8) and GATA binding protein 3 (GATA3)." (PMID 36862889, 2023).
follicular adenomas (12 papers, 2004 to 2025). "Regarding benign tumors and precursor lesions, PAX8 expression is confirmed in thyroid follicular adenomas and renal oncocytomas, both of which show strong and diffuse immunoreactivity." (PMID 40506992, 2025). "In benign tumors and precursor lesions, PAX8 expression is confirmed in thyroid follicular adenomas and renal oncocytomas, both of which demonstrate strong and diffuse immunoreactivity." (PMID 40506992, 2025). "Recently, our group and others have detected the expression of PAX8-PPARγ gene not only in FTCs but also in follicular thyroid adenomas (FTAs)." (PMID 15238980, 2004). "PAX8/PPARγ rearrangements were detected in about 2%–10% of follicular adenomas, as in the fvPTC." (PMID 35197932, 2022). "Chromosomal rearrangement resulting in a fusion gene, PAX8/PPARγ, may be involved in follicular adenoma (FA) to FTC progression." (PMID 27158284, 2015). "The PAX8/PPARγ rearrangement, producing the PAX8–PPARγ fusion protein (PPFP), is rare in follicular adenomas." (PMID 38791384, 2024). "This appears also to be case for PAX8/PPARγ rearrangements, that were originally discovered in FTC and, later on, in follicular adenomas and follicular variant of PTC; PAX8/PPARγ rearrangements are absent from all PDTC and UTC so far analysed." (PMID 22654560, 2011).
lung carcinoma (12 papers, 2010 to 2025). "Some researchers recommend using monoclonal PAX8 antibodies to exclude thyroid metastasis from some cancers, especially lung cancers." (PMID 39980562, 2025). "Initial misdiagnosis as lung cancer underscores the necessity of multidisciplinary collaboration and advanced IHC (e.g., PAX8, P504s) to confirm renal origin." (PMID 41280897, 2025). "In that study, 69.2% of thymus origin cancers showed PAX8-positive results compared to 5.8% in lung cancer patients." (PMID 34540435, 2021). "In another small study on 13 thymic cancer cases and 15 poorly differentiated lung cancer cases, patients were analyzed for PAX8 expression." (PMID 34540435, 2021). "The expression of PAX5 and PAX8 are different in lung cancer tissues in order to further identify potential therapeutic targets, while PAX5 inclined to expressed in SCLC cells, overexpression of PAX8 in most NSCLC cell lines." (PMID 29997452, 2018). "The remaining cancer samples, including breast, lung and colon cancer samples, had similar patterns of large 3D clusters/CK7+/PAX8- with AUC of 0.882, especially for lung cancer." (PMID 30024911, 2018). "Importantly, the phenotype is specific to ovarian cells, while lung cancer cells are inert to PAX8 targeting." (PMID 33903593, 2021). "We have previously shown differential expression of PAX5 and PAX8 in lung cancer." (PMID 24628993, 2014). "For instance, thymic carcinoma cells more strongly express PAX8, CD5, and CD117 compared to lung cancer cells." (PMID 40506992, 2025). "Thymic carcinoma cells, for instance, more strongly express PAX8, CD5, and CD117 compared to lung cancer cells." (PMID 40506992, 2025). "Multiple studies have reported positive PAX8 staining in several lung cancer specimens using polyclonal PAX8 antibodies rather than monoclonal PAX8 antibodies." (PMID 39980562, 2025). "Regarding PAX8 and PAX9, recent scientific studies have linked these transcription factor to lung cancer, despite their expression not being required in the lung under physiological conditions." (PMID 40506992, 2025). "Therefore, PAX8 and PAX9 play distinct roles in lung cancer biology, diagnostics, and potential therapeutic applications." (PMID 40506992, 2025). "However, we have previously shown that PAX5 and PAX8 are differentially expressed in lung cancers; while PAX5 expression is restricted to SCLC cells, PAX8 expression is apparent more in NSCLC cell lines." (PMID 24628993, 2014).
thyroid hypoplasia (12 papers, 2009 to 2025). Thyroid hypoplasia is a form of thyroid dysgenesis characterized by incomplete development of the thyroid gland that results in primary congenital hypothyroidism, a permanent thyroid deficiency that is present from birth. "Defective mutations in the PAX8 gene are generally associated with thyroid dysgenesis, most commonly presenting as thyroid hypoplasia or an ectopic thyroid gland." (PMID 40362701, 2025). "The authors observed that compound heterozygous mutations of the Tift1 and Pax8 genes resulted in thyroid hypoplasia." (PMID 41303336, 2025). "A comprehensive, phenotype-driven, Sanger sequencing approach was used to identify genetic mutations underlying CH, by sequentially screening known dyshormonogenesis-associated genes and TSHR in GIS cases and TSHR and PAX8 in cases with thyroid hypoplasia." (PMID 32765423, 2020). "We screened a hypothyroid child with thyroid hypoplasia for mutations in PAX8, TSHR, NKX2.1, NKX2.5 and FOXE1 genes." (PMID 25146893, 2014). "Autosomal dominant transmission of congenital thyroid hypoplasia due to loss-of-function mutation of PAX8 suggests a possible haploinsufficiency effect." (PMID 25484916, 2014). "Isolated thyroid hypoplasia may occur because of PAX8 or TSHR mutations, and mutations in the transcription factors NKX2-1 and FOXE1 cause CH in association with more extensive developmental syndromes." (PMID 32765423, 2020). "In humans, PAX8 mutation carriers have been reported to be hypothyroids with thyroid hypoplasia." (PMID 25146893, 2014). "Monogenic mutations causing dyshormonogenesis may underlie GIS CH; additionally, a small proportion of thyroid hypoplasia has a monogenic cause, such as TSHR and PAX8 defects." (PMID 32765423, 2020). "For instance, while heterozygous PAX-8 mutations in murine models do not display a pathological phenotype, heterozygous PAX-8 mutations have been reported in sporadic and familial CH patients with thyroid hypoplasia or ectopy." (PMID 30304112, 2018). "Not formally quantitating thyroid gland size might have failed to ascertain cases with mild thyroid hypoplasia, harboring mutations in some thyroid-dysgenesis associated genes (eg, PAX8, Nkx2–1)." (PMID 27525530, 2016).